BRCA2 (BRCA2 DNA repair associated)
Diseases named in the same sentence as BRCA2 in open-access papers (continued):
Sharing a sentence is not in itself a finding about the gene and the disease.
breast cancer (continued). "Breast cancer diagnoses ≤ 45 years of age was associated with a more modest, but statistically significant, risk of carrying a PV in BRCA2 (OR 1.98, 95% CI 1.84–2.14)." (PMID 37084156, 2023). "Although prophylactic surgery reduces the risk of mammary neoplasm in BRCA1/BRCA2 mutation carriers, it has drawbacks related to early menopause." (PMID 36835955, 2023). "For women carrying BRCA1 and BRCA2 P/LP germline variants, the cumulative breast cancer risks to age 80 are estimated at 72% and 69%, respectively." (PMID 37628558, 2023). "In the retrospective analysis, taller height was associated with risk of premenopausal breast cancer for BRCA2 variant carriers (HR 1.20 per 10 cm increase, 95% CI 1.04–1.38)." (PMID 37340476, 2023). "Among those who were homozygous for the ALDH2-rs10744777 T allele, the OR for developing breast cancer associated with the BRCA2 p.K3326* mutation was 1.72 (95% CI: 1.19–2.48, P = 0.003)." (PMID 37943872, 2023). "Nonetheless, the rate of non-BRCA pathogenic variations was higher than those of BRCA1 or BRCA2 pathogenic variations especially in bilateral breast cancer patients." (PMID 36896237, 2023). "We found that this operation was not linked with a reduced risk of developing breast cancer when considering both BRCA1 and BRCA2 carriers together but was linked with a reduced risk of breast cancer when considering BRCA2 carriers alone." (PMID 36900415, 2023). "BRCA1 and BRCA2 gene mutations are inherited and increase the likelihood of developing mammary tumors from early adulthood." (PMID 37835752, 2023). "The biggest risk factors are age, mutations in breast cancer genes 1 or 2 (BRCA1 or BRCA2), and dense breast tissue." (PMID 36900322, 2023). "In men, the main cause is disorder of the endocrine function of the testicles, as well as genetic mutations predisposing to the disease, including a mutation in the BRCA2 gene (breast cancer 2 gene)." (PMID 36983412, 2023). "BRCA1 and BRCA2 were the first two genes identified as having been associated with increased risk for breast cancer, when there is a mutation of either one." (PMID 37181043, 2023). "The Talazoparib Beyond BRCA (TBB) trial included any solid tumor with germline or somatic mutations in HR-related genes other than BRCA1 and BRCA2 in cohort B. They reported a 31% overall response rate in breast cancer patients." (PMID 38098088, 2023). "P/LP variants in cancer-predisposing genes like BRCA1 and BRCA2 account for 5%–10% of breast cancer cases." (PMID 37920853, 2023). "BRCA1 and BRCA2 (BReast CAncer genes 1 and 2) are well-known tumor suppressor genes linked to breast cancer." (PMID 36831644, 2023). "Herein, we report clinical and genetic details of a woman with breast cancer caused by the mosaic c.9648+1G>A variant in BRCA2." (PMID 36833429, 2023). "It has been demonstrated that breast cancers with BRCA1 mutations are more likely to be of high histological grade or triple-negative compared with tumors with a BRCA2 mutation." (PMID 37173992, 2023). "Early epidemiological studies highlighted an association between women with breast cancer and sarcomas in their relatives, and a high prevalence of childhood cancers in families with mutations in BRCA2 has also been described." (PMID 36585449, 2023). "In a third study, gene-based burden testing showed that there was an increase in carriers with BRCA1 and BRCA2 loss of function variants for breast cancer patients with an additional lung cancer." (PMID 37461096, 2023). "By the age of 70, individuals with BRCA1 mutations had an estimated breast cancer penetrance of 64.6% (95% CI = 59.5% to 69.4%), while those with BRCA2 mutations had a penetrance of 61.0% (95% CI = 48.1% to 72.5%)." (PMID 37781206, 2023). "Screening for germline pathogenic BRCA1 or BRCA2 variants (gBRCA) in high-risk breast cancer patients is known to be cost-effective in high-income countries." (PMID 38162618, 2023).
breast cancer (continued). "BRCA2-associated breast cancers are more likely to be found in the “luminal type” and share common characteristics with sporadic tumors." (PMID 37239058, 2023). "We performed whole-genome sequencing on matched tumour and normal samples from high-risk non-BRCA1/BRCA2 breast cancer families to understand the germline and somatic mutational landscape and mutational signatures." (PMID 37316882, 2023). "Knowing the BRCA1 and BRCA2 (BRCA1/2) gene mutation status can improve breast cancer patients’ health outcomes by guiding targeted treatment towards preventing breast cancer recurrence and other BRCA-related cancers." (PMID 36834079, 2023). "Mutations in the tumor suppressor genes BRCA1 and BRCA2 are responsible for the majority of hereditary breast cancer cases." (PMID 37138170, 2023). "Two recent large studies demonstrated that CHEK2 is the second most frequently altered breast cancer predisposition gene among patients of European descent, surpassed by BRCA2 and followed by BRCA1 in frequency of germline pathogenic variants." (PMID 37449874, 2023). "While there are mutations like BRCA2 in BCa that direct therapies, genetic factors play a smaller role in PCa compared to breast cancer." (PMID 37965470, 2023). "This population-based study is unique as 85% of all breast cancer cases diagnosed in the period of 1980–2004 in Iceland were tested for the 999del5 BRCA2 founder mutation." (PMID 38036573, 2023). "Of the 79 women with a personal history of breast cancer, 52 (65.8%) had P/LP variants in BRCA2 gene, while 27 (34.2%) had P/LP variants in BRCA1 gene." (PMID 36971799, 2023). "Whilst no specific variants dominated the pool, in general terms BRCA2 variants were associated with cancer and BRCA2 confirmed PVs were strongly associated with breast cancer collectively (p = 8e−06)." (PMID 37306523, 2023). "utilized matched samples of a PARP-inhibitor-sensitive and -resistant BRCA2-mutated mammary tumor to measure drug response in breast tumor organoids." (PMID 37781203, 2023). "Of all 2817 eligible women diagnosed with breast cancer in Iceland during 1980–2004, 85% had been tested for the Icelandic 999del5 BRCA2 (c.771_775delTCAAA) founder pathogenic variant." (PMID 38036573, 2023). "Women with pathogenic variants in BRCA1 and BRCA2 genes are considered a high-risk category for breast cancer having a lifetime risk of developing a breast malignancy of 85% and 40–45%, respectively." (PMID 38017478, 2023). "Although we did not have sequencing data available from the original tumor of patient #26, the #26 PDO had mutations typically present in breast cancer, such as mutations in BRCA2, FGFR2, and PMS2." (PMID 37423299, 2023). "Mutations of BRCA1 and BRCA2 genes significantly impact the DNA repair system, accounting for approximately 2–3% of breast cancer events and over 10% in TNBC." (PMID 37237509, 2023). "We find that mutations in FBH1 co-occur with mutations in the breast cancer susceptibility gene BRCA2 and other DNA damage repair genes." (PMID 37760409, 2023). "On the other hand, BRCA2 c.1310_1313delAAGA mutation carriers were more likely to be diagnosed with breast cancer already spread to regional lymph nodes." (PMID 37055759, 2023). "The HRR signature is strongly associated with germline and somatic mutations in BRCA1 and BRCA2 mutations in human breast cancer." (PMID 37805590, 2023). "These include mutations in the breast cancer type 1 and 2 susceptibility gene (BRCA1 and BRCA2); a mutation in one of these genes is associated with a 55–70% probability of developing breast cancer." (PMID 37108425, 2023).
breast cancer (continued). "c-Myc directly targets the miR-1245 promoter and enhances its expression, as well as causing downregulation of BRCA2 DNA repair-associated (BRCA2) gene expression and suppressing the ability for homologous recombination in breast cancer cells." (PMID 36835100, 2023). "This study aimed to conduct a network meta-analysis to assess the efficacy and safety of various pharmacotherapies for patients with metastatic, locally advanced, or recurrent breast cancer carrying BRCA1/BRCA2 pathogenic variants." (PMID 36865806, 2023). "The study found that BRCA1 and BRCA2 mutations were present in 2.5% and 3.7% of breast cancer patients, respectively, while PALB2 mutations were present in 0.6% of then." (PMID 38098088, 2023). "Recently, the OlympiA phase 3 trial showed that patients with high-risk, HER2-negative early breast cancer who have germline BRCA1 or BRCA2 pathogenic or likely pathogenic alterations benefited from adjuvant olaparib." (PMID 37173992, 2023). "Herein, we describe a case of a patient with breast cancer with a BRCA2 pathogenic variant that was resistant to olaparib and was suspected to be a reversion mutation based on cancer genomic profiling." (PMID 37361653, 2023). "By the age of 80, women with BRCA1 and BRCA2 gene mutations have a cumulative risk of 72% and 69%, respectively, of developing breast cancer." (PMID 37835752, 2023). "These include mutations in genes BRCA1 and BRCA2, associated with a 50-85% lifetime risk of breast cancer." (PMID 37750138, 2023). "Within the 7 breast cancer cases, two cases showed a BRCA2 nonsense variant (p.R2318* and p.K3326*), one case showed ERBB3 G234R, one case showed KRAS G12V, and one case showed ARID1A P453fs." (PMID 36125633, 2023). "55%–65% of BRCA1 mutation‐containing females and 45% of BRCA2 mutation‐containing females have a probability of developing breast cancer after the age of 70 years." (PMID 36971312, 2023). "Genetic mutations have been reported to associate with ovarian cancer progression, such as BRCA1 (breast cancer 1) mutation and BRCA2 (breast cancer 2) mutation." (PMID 38152652, 2023). "Our data showing Brca2mut/WT HR- luminal cell expansion raise important questions about the aetiology of BRCA2-associated breast cancers." (PMID 37626143, 2023). "Pathogenic variants of breast cancer susceptibility genes 1 or 2 (BRCA1/BRCA2) reportedly occur in nearly 5% of patients with breast cancer." (PMID 36865806, 2023). "We previously reported the distribution and frequency of germline BRCA1 and BRCA2 variants in high-risk Jordanian breast cancer patients, chosen in accordance with international guidelines." (PMID 37920853, 2023). "Estrogen receptor-positive (ER+) breast cancer generally confers a more favorable prognosis than ER-negative cancer, however, a different picture is emerging for BRCA2 mutation carriers and young patients." (PMID 38036573, 2023). "The discovery of BRCA1 and BRCA2 pathogenic variants in women with breast cancer in the 1990s paved the way for the expansion of personalized cancer care." (PMID 37623478, 2023). "OLA, a potent cytotoxic anticancer drug, is administrated for the treatment of patients with advanced, recurrent ovarian cancer who have mutations of breast cancer BRCA1 or breast cancer BRCA2." (PMID 37376117, 2023). "Regarding tumor subtypes, BRCA1 breast cancers were associated with a TN subtype, whereas BRCA2 breast cancers were associated with a luminal subtype." (PMID 36905492, 2023). "Another systematic review evaluated the evidence of dietary habits, weight status/change, and physical activity on ovarian and breast cancer risk among women with BRCA1/BRCA2 P/LP germline variants." (PMID 37628558, 2023). "Pathogenic germline variants in the BRCA1 and BRCA2 genes are present in 3% of all breast cancer cases." (PMID 36112334, 2023). "Women who inherit a BRCA1 or BRCA2 mutation have a substantial risk of developing breast cancer, which is estimated to be 72% and 69%, respectively." (PMID 37138170, 2023).
breast cancer (continued). "Most commonly, two mutated genes, including breast cancer 1 (BRCA1) and breast cancer 2 (BRCA2) who were inherited, causing ovarian cancer and breast cancer in women." (PMID 36608061, 2023). "The prevalence of BRCA1 or BRCA2 germline pathogenic mutations is approximately 5% in patients with breast cancer." (PMID 37173992, 2023). "Combining SOC with gefitinib in BRCA2-mut ER+/HER2+ breast cancer cell lines also caused mostly synergistic growth inhibition, accompanied by induction of DNA damage, G1 arrest and apoptosis." (PMID 37914699, 2023). "The prevalence of the BRCA1 and BRCA2 mutations among Asian Americans with strong personal and/or family history of breast cancer was about 11.5% and 13%, respectively." (PMID 36834079, 2023). "High to moderate penetrant mutations in breast cancer predisposition genes, such as BRCA1 and BRCA2, are rare in large populations and account for only 5–10% of total breast cancer cases." (PMID 36315068, 2023). "The lifetime risk of PDAC is about 1% for BRCA1 and 4.9% for BRCA2 PV/LPVs carriers, and studies by the Breast Cancer Linkage Consortium reported a 2.3-fold and 3.5-fold increased risk of PDAC in carriers of BRCA1- and BRCA2-altered variants, respectively." (PMID 37046793, 2023). "Taller height was associated with higher premenopausal breast cancer risk in BRCA2 pathogenic variant carriers (HR 1.20 per 10 cm increase, 95% CI 1.04–1.38)." (PMID 37340476, 2023). "To date, BRCA1 and BRCA2 are the most common and widely studied breast cancer susceptibility genes, accounting for up to 40% of familial breast cancer." (PMID 36980802, 2023). "But known risk genes (BRCA1/BRCA2 and others) are insufficient to explain all inherited breast cancer risk." (PMID 36702877, 2023). "Fanconi anemia is also brought on by germline homozygous loss of function (LoF) mutations of PALB2, like BRCA2, although heterozygous LoF mutations have been associated with hereditary breast cancer and pancreatic cancer." (PMID 37732318, 2023). "Among the 91 men diagnosed with breast cancer, 12 (P/LP) variants were identified (13%); 7/91 displayed a mutation in BRCA2 and 2/91 in PALB2." (PMID 37444530, 2023). "In this study, we found that women at high risk of developing breast cancer due to an inherited BRCA1 or BRCA2 mutation who used vitamin D supplements had 46% lower odds of having breast cancer." (PMID 37345127, 2023). "The risk of breast cancer in BRCA2 mutation carriers is comparatively lower, with an average cumulative risk of 39% for women born before 1920 and up to 51% for those born after 1950." (PMID 37623478, 2023). "This increase is similar in magnitude to BRCA1 and BRCA2 gene variants and breast cancer risk, which are far less common (prevalence of 0.2–0.3%) and trigger more frequent cancer screening." (PMID 36651198, 2023). "Approximately 11.2% of patients with TNBC carry germline variants in BRCA1 or BRCA2 genes, and they are usually diagnosed at a younger age and have a positive family history of breast cancer." (PMID 37656691, 2023). "For example, BRCA1 and BRCA2 variants are found in only 1 in 400 women, but are associated with a full lifetime breast cancer risk of over 50%." (PMID 36749458, 2023). "Pathogenic variants in BRCA1 and BRCA2 confer a high life-time risk of breast cancer and increased risk of ovarian cancer." (PMID 37173335, 2023). "Among patients and the established breast cancer susceptibility genes, PTVs in BRCA2 and ATM, followed by PALB2, and BRCA1, were the most prevalent." (PMID 37790698, 2023). "Mutations in the breast cancer susceptibility gene, BRCA2, greatly increase the lifetime risk of developing breast and ovarian cancers." (PMID 36976771, 2023). "Secondly, heterozygous hypomorphic germline mutations in BRCA2 + RAD51C are also found in families with a history of breast cancer susceptibility." (PMID 36906610, 2023).
breast cancer (continued). "Regarding BRCA2 germline variant carriers, of 11 patients with breast cancer, 3 received tamoxifen and 8 had a placebo (RR 0.38; 95% CI, 0.06–1.56)." (PMID 37628558, 2023). "Carriers of germline pathogenic variants in the BRCA1 or BRCA2 breast cancer predisposition genes have high breast cancer risks." (PMID 37340476, 2023). "BRCA1 and BRCA2 pathogenic variants account for 90% of hereditary breast malignancies, incurring a lifetime breast cancer risk of 85% and 40–45% respectively, in affected individuals." (PMID 38017478, 2023). "We report evidence of PTV association with overall breast cancer risk for BRCA2 and ATM with adjusted ORs of 9.75 (1.81-52.69 95% CI, p-value = 0.0081) and 7.61 (1.32-43.97 95% CI, p-value = 0.023)." (PMID 37790698, 2023). "Inherited mutations in BRCA1 and BRCA2 predispose individuals to high risks of breast and ovarian cancers, with lifetime risks of breast cancer as high as 80% in the US." (PMID 37370892, 2023). "Women who have a genetic mutation of BRCA1 or BRCA2 are at a significantly higher risk for developing breast cancer." (PMID 37370730, 2023). "For example, in a previous study, the yield of BRCA1 and BRCA2 gene sequencing in ethnic Lebanese Arab women with high hereditary-risk breast cancer was much lower than predicted when compared to women of other ethnicities of the same age." (PMID 38201524, 2023). "We also examined three other mutations: the A1108G mutation found in canine mammary tumor samples in the previous report, and S1114P and T1115P, corresponding to human BRCA2 S1115P and T1116P mutations, respectively, in breast cancer samples." (PMID 36851449, 2023). "Germline mutations in BRCA1 and BRCA2 genes not only increase the risk of breast and ovarian cancer, but also contribute to the susceptibility of pancreatic and prostate cancer." (PMID 38274092, 2023). "Women with BRCA mutation (BRCA1 or BRCA2) have a substantially 69–72% increased risk of developing breast cancer." (PMID 37406000, 2023). "Pathogenic variants in the BRCA1 and BRCA2 genes are responsible for approximately 20% of hereditary breast cancers." (PMID 37239898, 2023). "Unnafected female carriers of BRCA1 and BRCA2 pathogenic/likely pathogenic variants (P/LPVs) are at higher risk of breast cancer (BC) and ovarian cancer (OC)." (PMID 36831416, 2023). "Hereditary pathogenic/likely pathogenic variants (P/LPVs) of BRCA1 and BRCA2 genes are the leading genetic causes of breast cancer (BC), ovarian cancer (OC), and other cancers (prostate, pancreas)." (PMID 36831416, 2023). "Screening for the germline mutations c.5309G>T and BRCA2 c.1310_1313delAAGA was performed by sequencing on a total of 184 breast cancer (BC) patients originated from the Northeastern region of Morocco." (PMID 37055759, 2023). "Hereditary pathogenic/likely-pathogenic variants (PVs/LPVs) of BRCA1 and BRCA2 genes are the principal genetic cause of breast cancer (BC), ovarian cancer (OC), and other malignancies such as prostate (PrC) and pancreas (PC) carcinomas." (PMID 37046793, 2023). "Female BRCA1/BRCA2 (=BRCA) pathogenic variants (PVs) carriers are at a substantially higher risk for developing breast cancer (BC) compared with the average risk population." (PMID 37370730, 2023). "BRCA1 and BRCA2 mutation carriers have a ~17–44% risk of ovarian cancer (OC) and ~69–72% risk of breast cancer (BC)." (PMID 36900415, 2023). "BRCA1 and BRCA2 (heretofore BRCA) germline pathogenic variant (PVs) carriers are at a significantly higher risk for breast cancer (BC), with estimated cumulative lifetime risk of 55% to 65% and 45% to 47%, respectively." (PMID 37370730, 2023). "Multiple breast cancer cluster regions (BCCR) and ovarian cancer cluster regions (OCCR) have been observed in BRCA1 and BRCA2 and are associated with relatively elevated breast cancer risk and lower ovarian cancer risk or inversely." (PMID 35469032, 2022).